PPAN (peter pan homolog)
Description:
May have a role in cell growth.
Synonyms: Ssf-1; BXDC3; SSF1; SSF2; SSF
Tractability: Small molecule: a structure with a bound ligand is known. PROTAC: ubiquitination databases record sites on it; its protein half-life has been measured.
Gene: Protein-coding gene on chromosome 19 (10,106,329 to 10,112,012, forward strand). Ensembl gene ENSG00000130810.
Subcellular location: Nucleus, nucleolus
Gene Ontology:
Molecular function: RNA binding; rRNA binding
Biological process: maturation of LSU-rRNA from tricistronic rRNA transcript (SSU-rRNA, 5.8S rRNA, LSU-rRNA); rRNA processing
Cellular component: nucleus; preribosome, large subunit precursor; nucleolus
Genetic constraint (gnomAD): Loss-of-function variants: 39 observed, 47.63 expected, observed/expected ratio (o/e) 0.82, 90% interval 0.63 to 1.07. The synonymous counts are far from expectation, so gnomAD's model fits this gene poorly and the ratio says little. Missense variants: 736 observed, 652.87 expected, observed/expected ratio (o/e) 1.13, 90% interval 1.06 to 1.2. Synonymous variants: 315 observed, 260.69 expected, observed/expected ratio (o/e) 1.21, 90% interval 1.1 to 1.33.
Homologues: Orthologues: chimpanzee PPAN (99% identical), macaque PPAN (87% identical), pig PPAN (80% identical), dog PPAN (79% identical), mouse Ppan (74% identical), rat Ppan (73% identical), guinea pig PPAN (64% identical), tropical clawed frog ppan (57% identical), zebrafish ppan (56% identical), Drosophila melanogaster ppan (35% identical), Caenorhabditis elegans lpd-6 (33% identical).
Diseases named in the same sentence as PPAN in open-access papers:
PPAN is named in the same sentence as 8 diseases in open-access papers, as found by Europe PMC text mining. Sharing a sentence is not in itself a finding about the gene and the disease. The quoted sentences say what the papers report.
cervical cancer (2 papers, 2019 to 2021). A primary or metastatic malignant neoplasm involving the cervix. "We have previously shown that endogenous PPAN specifically localizes to mitochondria in HeLa cervical cancer cells, besides its well-known localization to nucleoli." (PMID 31416196, 2019). "Besides other targets, siRNA mediated knockdown of PPAN resulted in upregulation of the autophagy factor ATG7 in HeLa cervical cancer cells when using the functional PPAN si RNA, termed si PPAN-B as previously." (PMID 34944838, 2021). "Indeed, the effect on both factors could be reproduced by two independent and functional PPAN siRNAs (si PPAN-A and -B) in the cervical cancer cell line HeLa." (PMID 34944838, 2021).
colorectal cancer (1 paper, 2019). A primary or metastatic malignant neoplasm that affects the colon or rectum. "Here, we first recapitulated the mitochondrial localization of endogenous PPAN in different cancer cell lines such as HCT116 colorectal cancer and U2OS osteosarcoma cells by co-localization with the mitochondrial inner membrane marker TIM23 (translocase of the inner membrane 23)." (PMID 31416196, 2019).
cancer (3 papers, 2019 to 2021). A tumor composed of atypical neoplastic, often pleomorphic cells that invade other tissues. "We show that knockdown of the ribosomopathy factor SBDS, or of key ribosome biogenesis factors (PPAN, NPM, PES1) is associated with enhanced levels of ATG7 in cancer cells." (PMID 34944838, 2021). "Down-regulation of PPAN enhances autophagic flux in cancer cells." (PMID 31416196, 2019). "Moreover, PPAN knockdown activated autophagic flux in cancer cells." (PMID 34944838, 2021).
PPAN also shares sentences with these, for which no sentence is quoted: breast carcinoma (1 paper); infection (1); osteosarcoma (1); subarachnoid hemorrhage (1); tumor (1).